AKT1 (AKT serine/threonine kinase 1)
Diseases named in the same sentence as AKT1 in open-access papers (continued):
Sharing a sentence is not in itself a finding about the gene and the disease.
cervical carcinoma (215 papers, 2006 to 2026). A carcinoma arising from either the exocervical squamous epithelium or the endocervical glandular epithelium. "Online bioinformatic tools were used to conduct the pre-investigation of linc00958/miR-185-5p/RSF-1 and predict the associations between RSF-1 and AKT1/GSK3β/VEGFA in cervical cancer." (PMID 36056431, 2022). "SLC5A3 knockdown/KO significantly decreased the phosphorylation of Akt1 and S6K in primary cervical cancer cells." (PMID 37324953, 2023). "In contrast, supplementation of myo-inositol or n-acetyl-L-cysteine or transduction of a constitutively active Akt1 construct mitigated SLC5A3 KO-induced cytotoxicity in cervical cancer cells." (PMID 37324953, 2023). "Consistent with previous report, we found that the expression of YTHDF2 was evidently positively corrected with AKT1 expression in cervical cancer using GEPIA2 database." (PMID 36566195, 2022). "Protein rogdi homolog variant ROGDI:43–47, upregulated and reported as a target molecule in cervical cancer, was found downregulated in the AKT1 silenced sample compared to control (siNoN)." (PMID 35892586, 2022). "linc00958/miR-185-5p/RSF-1 modulates cisplatin resistance and angiogenesis through AKT1/GSK3β/VEGFA pathway in cervical cancer." (PMID 36056431, 2022). "Mechanistically, linc00958 regulated miR-185-5p and RSF-1 and modulated cisplatin resistance in cervical cancer cells via targeting AKT1/GSK3β/VEGFA pathway." (PMID 36438563, 2022). "For instance, circRNA-AKT1 contributed to cervical cancer progression via sequestering miR-942-5p to enhance AKT1 expression." (PMID 34507559, 2021). "All of these results further confirm that HK2 induces FN1, MMP2, and MMP9 expression by stimulating Akt1 (p-Akt1) in cervical cancer cells, subsequently enhancing cell motility." (PMID 34758823, 2021). "As shown in this study, exogenous expression of HK2 activated Akt1 (p-Akt1) in cervical cancer cells, subsequently enhancing cell motility and tumor metastasis by inducing FN1, MMP2 and MMP9 expression." (PMID 34758823, 2021). "The high expression of circ-AKT1 and AKT1 accelerated cervical cancer cell proliferation and invasion." (PMID 33413360, 2021). "Thereby, there is probably an interactive regulatory mechanism between HK2 and Akt1 (p-Akt1) during the malignant progression of cervical cancer." (PMID 34758823, 2021). "Further studies demonstrated that this promotion of cell motility by HK2 was probably a result of it inducing FN1, MMP2 and MMP9 expression by activating Akt1 in cervical cancer cells." (PMID 34758823, 2021). "There likely exists an interactive regulatory mechanism between HK2 and Akt1 during the malignant process of cervical cancer." (PMID 34758823, 2021). "The circRNA AKT1 can sponge miR-942-5p to affect the AKT1 expression, by enhancing the cervical cancer progression." (PMID 34108451, 2021). "For example, circRNA-AKT1 contributed to tumor progression in cervical cancer via decoying miR-942-5p and up-regulating AKT1." (PMID 33292255, 2020). "Cervical cancer cells were transfected with AKT1 or AKT2 siRNA and subjected to irradiation treatment." (PMID 32711558, 2020). "Li and coworkers found that ERBB2 activated downstream Myc and promoted cells proliferation by phosphorylating AKT1 and Erk1/2 in cervical cancer." (PMID 30123134, 2018). "In the present study, we found that the expression level of AKT1, p-AKT1 (Ser473), and p-GSK3β (Ser389) were decreased in cervical cancer cells treated with Bufalin, but the expression of GSK3β was increased." (PMID 26758421, 2016). "All of these results further confirmed that Slug inhibited cell proliferation and tumor formation of human cervical cancer cells via trans-suppressing Akt1/p-Akt1 through both the p21/p27 proteins and the Wnt/β-catenin signaling pathway." (PMID 27036045, 2016). "Secondly, MK-2206 (MK-2206), which is an inhibitor of Akt1, was used in all of the Slug-modified the cervical cancer cells investigated in this study." (PMID 27036045, 2016).
cervical carcinoma (continued). "The next protein is AKT1, whose abnormality leads to defective signaling in many human cancers and mutations in the AKT pathway responsible for cervical cancer." (PMID 26308848, 2015). "Recently, a cancer-promoting role through activation of the ERK and AKT1 pathways has been described for miR-133b in other cervical cancer models." (PMID 22532850, 2012). "Our study demonstrated that HDAC inhibitors, such as valproic acid and butyrate, induce apoptosis in HeLa cervical cancer cells by inhibition of gene expression of Akt1 and Akt2." (PMID 17156483, 2006). "Further, linc00958/RSF-1 downregulation or miR-185-5p upregulation could alleviate the cisplatin resistance and tube formation in cervical cancer cells via AKT1/GSK3β/VEGFA pathway." (PMID 36056431, 2022). "However, further research is still necessary to investigate the potential molecular mechanism through which HK2 upregulates Akt1 mRNA expression and stimulates p-Akt1 expression in cervical cancer cells." (PMID 34758823, 2021). "HK2 and Akt1 (p-Akt1) probably act as regulators of each other in cervical cancer cells and synergistically promote malignant growth and distant metastasis during the development of cervical cancer." (PMID 34758823, 2021). "In conclusion, this study demonstrated that HK2 could activate Akt1 (p-Akt1) in cervical cancer cells, subsequently enhancing cell motility and tumor metastasis by inducing FN1, MMP2, and MMP9 expression." (PMID 34758823, 2021). "Studies have shown that miR-942-5p affects EMT by regulating AKT1 expression in cervical cancer." (PMID 33997050, 2021). "This study demonstrated that HK2 could activate Akt1 in cervical cancer cells, subsequently enhancing cell motility and tumor metastasis by inducing FN1, MMP2 and MMP9 expression." (PMID 34758823, 2021). "Likewise, E7 involvement in PI3K/AKT1 activation and was relevant during the progression of cervical cancer, while, regarding the EGF pathway, Gefitinib incubation did not alter Pirin levels." (PMID 32679705, 2020). "Additionally, miR-942-5p is sequestered by circRNA-AKT1 to induce AKT1 and contributes to cervical cancer progression." (PMID 33489916, 2020). "Therefore, the expression of Akt1/p-Akt1 was detected in the Slug-modified cervical cancer cells and their controls by western blotting." (PMID 27036045, 2016). "All of the cervical cancer cells subjected to the MK treatment grew much more slowly and expressed less Akt1/p-Akt1, more p21/p27, less p-Rb and fewer molecules (p-GSK3β, β-catenin, c-myc and cyclin D1) of the Wnt/β-catenin signaling pathway than the cells that were not subjected to MK treatment." (PMID 27036045, 2016). "All of these results suggested that Slug could inhibit the proliferation of cervical cancer cells by up-regulating the p21/p27 proteins by trans-suppressing the expression of the Akt1/p-Akt1 proteins." (PMID 27036045, 2016). "This study reported for the first time that Slug could inhibit proliferation and tumor formation in human cervical cancer cells by up-regulating p21/p27 and/or down-regulating cyclin D1 via the trans-suppression of Akt1/p-Akt1." (PMID 27036045, 2016). "All of these data indicated that Slug could trans-suppress the expression of Akt1/p-Akt1 in cervical cancer cell lines." (PMID 27036045, 2016). "In the present study, we demonstrated that Slug could trans-suppress Akt1/p-Akt1 expression (p < 0.05) in cervical carcinoma cells and then decrease the phosphorylation of GSK3β (p < 0.05) by Akt1." (PMID 27036045, 2016). "Interestingly, although a significantly increased protein level of Akt1/p-Akt1 was observed in HK2-overexpressing cervical cancer cells, when such elevated Akt1/p-Akt1 expression was inhibited by using MK2206, the protein level of HK2 was also significantly diminished in HK2-overexpressing cells." (PMID 34758823, 2021).
cervical carcinoma (continued). "Therefore, in the Slug-modified cervical cancer cells, cell proliferation and tumor formation should be affected by the cyclin D1 protein through the Wnt/β-catenin signaling pathway via the trans-suppression of the expression of the Akt1/p-Akt1 proteins." (PMID 27036045, 2016). "Additionally, we demonstrated that Slug could trans-suppresses Akt1/p-Akt1 protein expression and simultaneously up-regulates p21/p27 protein expression in all cervical cancer cells (p < 0.05)." (PMID 27036045, 2016). "However, further experiments will be required to determine whether the up-regulation of p21/p27 by Slug is also caused by the decreased phosphorylation of p21/p27 through the trans-suppression of Akt1/p-Akt1 in cervical carcinoma cells." (PMID 27036045, 2016). "AKT1 was identified as a potential target of β-lapachone in modulating glucose metabolism and EMT in cervical cancer cells." (PMID 40051559, 2025). "Transforming growth factor beta (TGF-β) can upregulate circ_0033550 to promote AKT1 and EMT expression in cervical cancer cells." (PMID 36230902, 2022). "All of these results demonstrate that stimulated HK2 expression induces Akt1 (p-Akt1), FN1, MMP2 and MMP9 expression in cervical cancer cells." (PMID 34758823, 2021). "The correlation between HK2 and Akt1, p-Akt1, FN1 expression in cervical cancer cells and human squamous cervical carcinoma (SCC) samples was verified in this study." (PMID 34758823, 2021). "The expression of p-ErbB2, p-AKT1, p-Erk1/2, CyclinD1 and CyclinE1 was up-regulated and the expression of p21 was down-regulated in GDF15-overexpressing and rhGDF15-treated cervical cancer cells." (PMID 29636108, 2018). "Meanwhile, there was no significant expression level of AKT1 (p > 0.1452) in the L. cornuta-treated cervical cancer cells compared to the NC." (PMID 39005932, 2024). "AKT1 and AKT2 expression was present in all three cervical cancer cell lines (Fig. S4BCD)." (PMID 34469022, 2021). "In addition, TGF-β induced the expression of circ-AKT1 and AKT1 and promoted EMT in cervical cancer." (PMID 33413360, 2021). "Among the eight nonresponder patients with cervical cancer, four received everolimus on the basis of PIK3CA mutation (Glu545Lys), two on the basis of PTEN inactivation, and two on the basis of AKT1 mutation (Glu17Lys)." (PMID 32914004, 2018). "As a result, miR-let-7c-5p/insulin-like growth factor 1 receptor/phosphatidylinositol-3 kinase/AKT serine/threonine kinase 1 (miR-let-7c-5p/IGF-1R/PI3K/AKT) and beta-catenin/snail family transcriptional repressor 2 (β-catenin/SLUG) were highlighted as potential targets against cervical cancer." (PMID 37576994, 2023). "In this study, the protein levels of both Akt1 and p-Akt1 were significantly increased in HK2-overexpressing cells but reduced in HK2-knockdown cells, suggesting that the protein level of Akt1 (p-Akt1) was positively correlated with HK2 in cervical cancer cells." (PMID 34758823, 2021). "In HPV16 and AKT1 positive VIN, E7 expression was high and widespread not only in the nucleus, as has been reported previously in cervical cancer, but also in the cytoplasm in some VIN." (PMID 22685591, 2012).
Obesity (184 papers, 2009 to 2026). Accumulation of substantial excess body fat. "Studies have demonstrated that AKT1 deficiency in mice enhances energy expenditure and prevents diet-induced obesity." (PMID 40438591, 2025). "AKT1 is implicated in metabolic dysfunction-related conditions, including obesity, metabolic syndrome, and MASLD." (PMID 38755697, 2024). "Selective inhibition of AKT1 in adipose tissue represents a novel strategy for promoting energy expenditure to combat obesity and its associated metabolic diseases." (PMID 39409084, 2024). "Besides, overexpression of specific genes like AKT1 in adipocytes leads to the development of severe obesity causing glucose intolerance." (PMID 40024983, 2025). "Together, we speculate that the adipose-selective inhibition of Akt1 is a novel strategy to induce energy expenditure against obesity and its associated metabolic diseases." (PMID 30158592, 2018). "Obesity indirectly regulates de novo lipogenesis of fatty acids by controlling downstream AKT1 and SREBF1 through IL6." (PMID 39928768, 2025). "Our analysis identified multiple potential targets of OJ extract in obesity-induced muscle atrophy, with core nodes including AKT1, IL6, and CASP3." (PMID 41470891, 2025). "Many genes on this list are involved in different processes associated with T2DM development, such as obesity (SREBF1 and H6PD), inflammation (TGFB1), and insulin resistance (RPTOR and AKT1)." (PMID 39273245, 2024). "This choice was based on their strong protein-protein interactions and GO analysis, which highlighted the involvement of AKT1 and PPARG, genes that have been extensively associated with obesity." (PMID 39409084, 2024). "Our findings are strikingly similar to the observation that the overexpression of the AKT1 isoform increased muscle fiber size and reduced dietary-induced obesity, albeit our increases in AKT2 were more robust than the increases in AKT1." (PMID 39408607, 2024). "Meanwhile, animal experiments revealed that deletion of the transcription factor AKT1 increased energy expenditure and prevented diet-induced obesity in mice, and AKT1 regulated macrophage polarization and alters periodontal inflammatory status." (PMID 37063877, 2023). "Structure-based screening identified the dietary supplement adenosine as a promising safe AKT1 inhibitor, potentially mitigating the obesity-to-cancer transition." (PMID 37954072, 2023). "Obesity and hypertension share common susceptibility genes, such as genes Jun proto-oncogene (JUN), and serine/threonine kinase 1 (AKT1)." (PMID 37391689, 2023). "According to previous literature, the deletion of AKT1 increased energy consumption and prevented diet-induced obesity in mice." (PMID 35267929, 2022). "In a skeletal muscle‐specific Akt1 transgenic mouse, Akt1‐mediated growth of glycolytic muscle led to ameliorated obesity with improvement in insulin sensitivity and reductions in serum insulin and glucose." (PMID 34227742, 2021). "Taken together, these results reveal that Pi3K/Akt1/TOR signaling in the oenocyte protects against obesity." (PMID 33107824, 2020). "One PCOSrp (RAC-alpha serine/threonine-protein kinase, AKT1) was found to be involved in schizophrenia, depressive disorder, and obesity." (PMID 31216618, 2019). "Together, these studies demonstrate the role of butein in obesity and metabolic diseases, further highlighting that adipose PI3Kα–Akt1–Prdm4 axis is a regulator of energy expenditure." (PMID 30158592, 2018). "Effect of Metabolic Biomarker Levels on the relationship between IGF-I/IR signaling pathways–relevant SNPs (in AKT1/2 genes) and CRC risk, stratified by obesity status‡." (PMID 29023587, 2017). "AKT1 G205T genotype influenced obesity-related metabolic phenotypes and their responses to aerobic exercise training in older Caucasians." (PMID 24571688, 2014). "The specific aim of this study was to create a zebrafish obesity model by over expressing the insulin signaling hub of the Akt1 gene." (PMID 22623957, 2012).
Obesity (continued). "In contrast, deletion or loss of function mutations in myostatin, and conditional muscle-specific overexpression of Akt1, clearly protect against or reverse diet-induced obesity and hepatic lipid deposition." (PMID 20593012, 2010). "The study revealed a close correlation between obesity and the AKT1 and PPARG genes." (PMID 39409084, 2024). "The interest in AKT1 and PPARG proteins for anti-obesity purposes is substantial due to their close association with the PI3K/Akt and PPAR signaling pathways, which play crucial roles in obesity-related processes." (PMID 39409084, 2024). "EGCG may contribute to preventing obesity-related precocious puberty through targets such as AKT1, EGFR, ESR1, STAT3, IGF1, and MAPK1 and multiple signaling pathways, including the estrogen, PI3K-Akt, MAPK, and Jak-STAT pathways." (PMID 37334310, 2023). "Previous research had shown that lack of AKT1 expression could lead to increased energy consumption while preventing diet-induced obesity." (PMID 35267929, 2022). "Since one of the vital obesity genes: AKT1 has the high node diversity (367.89) in PPI network, which at molecular level not only mediated type II muscle growth and thus led to the reversible reduction of fat mass, but also have a direct role on cancer and hearing loss." (PMID 34848731, 2021). "For example, Akt1 overexpression in skeletal muscle can stimulate hypertrophy of glycolytic fibers, as is seen in myostatin-null muscle, and concomitant robust protection from obesity." (PMID 33220490, 2021). "Oenocyte-specific Pi3K/Akt1/TOR signaling protects against obesity." (PMID 33107824, 2020). "Consistent with one previous study showing that genetic variants in the insulin pathway were associated with CRC by interacting with lifestyle factors (e.g., diet), we found that several SNPs in the AKT1/2 genes were associated with CRC, by interacting with obesity, PA, and exogenous E use." (PMID 29023587, 2017). "Consistently, ablation of Akt1 mitigated the obesity and BAT dysfunction induced by DJ-1 transgene." (PMID 28224045, 2017). "Interestingly, deletion of Akt1 in DJ-1 transgenic mice can rescue DJ-1 overexpression-induced Ucp1 inhibition and obesity." (PMID 28224045, 2017). "We next asked whether Akt1 contributes to DJ-1-mediated obesity and we found that Akt1 deletion significantly decreased DJ-1 transgene-induced obesity." (PMID 28224045, 2017). "For example, in an individual tumor, AKT1/2 signaling might not be activated by a mutation; however, it might be activated by obesity." (PMID 36046651, 2022). "Collectively, these findings suggest that EA prevents HFD-induced obesity by alleviating intestinal oxidative stress and mitochondrial dysfunction through the modulation of the PPARG/STAT3/p-AKT1 signaling axis." (PMID 41829165, 2026). "Currently, there have been no Food and Drug Administration (FDA)-approved drugs targeting AKT1 and PPARG pathways specifically for regulating lipid metabolism in anti-obesity treatment." (PMID 39409084, 2024). "The study highlighted the significance of PI3K-Akt and PPAR signaling pathways, particularly focusing on AKT1 and PPARG, which demonstrated extensive protein-protein interactions among obesity-related genes." (PMID 39409084, 2024). "In the BC subnetwork, the targets with the top three BC values were albumin (ALB), interleukin-6 (IL6), and AKT serine/threonine kinase 1 (AKT1), which were considered the core targets connected with microbes to alleviate obesity." (PMID 36139478, 2022). "Molecular docking results also revealed that the hub target genes bound to melatonin with high affinity, particularly AKT1, PTGS2, and ERBB2, can be used to treat LR-induced obesity by melatonin." (PMID 35937803, 2022). "According to the PPI network analysis of hispidulin anti-obesity targets, SRC (proto-oncogene tyrosine-protein kinase Src), EGFR (epidermal growth factor receptor), and AKT1 (AKT serine/threonine kinase 1) were the top three genes based on the degree." (PMID 34944408, 2021).